SNORA53 (small nucleolar RNA, H/ACA box 53)
Synonyms: ACA53
Gene: Small nucleolar RNA gene on chromosome 12 (98,599,635 to 98,599,883, forward strand). Ensembl gene ENSG00000212443.
Gene Ontology:
Biological process: RNA processing
Cellular component: nucleolus
Homologues: Orthologues: chimpanzee SNORA53 (99% identical), macaque SNORA53 (98% identical), rabbit SNORA53 (92% identical), pig SNORA53 (91% identical), guinea pig SNORA53 (90% identical), mouse Gm24119 (88% identical), rat Snora53 (88% identical).
Diseases named in the same sentence as SNORA53 in open-access papers:
SNORA53 is named in the same sentence as 2 diseases in open-access papers, as found by Europe PMC text mining. Sharing a sentence is not in itself a finding about the gene and the disease. The quoted sentences say what the papers report.
glioblastoma (1 paper, 2020). The most malignant astrocytic tumor (WHO grade IV). "Further validation by RT-qPCR revealed SMIM30, SNORA53 and LINC01354 were significantly upregulated and EFEMP2 markedly downregulated in 15 glioblastoma samples compared to 6 controls samples." (PMID 32962742, 2020).
SNORA53 also shares sentences with these, for which no sentence is quoted: Sepsis (1 paper).